LEP (leptin)
Diseases named in the same sentence as LEP in open-access papers (continued):
Sharing a sentence is not in itself a finding about the gene and the disease.
type 2 diabetes (continued). "The results indicated that women in the DD group had significantly higher levels of IL-1β and leptin compared to the CN group (p < 0.05); however, this significance was lost upon adjustment to type 2 diabetes diagnosis." (PMID 40699752, 2025). "Leptin, present in the adipose tissue of type 2 diabetes patients, can elevate TSH levels, thereby boosting deiodinase activity, facilitating the conversion of FT4 to FT3, and augmenting basal metabolic rate." (PMID 39926348, 2025). "Leptin expression is increased in individuals with central obesity and type-2 diabetes and is mainly driven by the IL-23/Th17 axis in psoriatic patients." (PMID 40740781, 2025). "Protein tyrosine phosphatase 1B (PTP1B) is a crucial enzyme involved in regulating insulin and leptin signaling pathways, making it a promising target for treating type 2 diabetes." (PMID 41726330, 2025). "Cord blood glucose, insulin and leptin were increased in infants of type 2 diabetes mothers and increased leptin was positively correlated with maternal leptin and birth weight." (PMID 40045330, 2025). "MiR-203a-3p, which is predicted to directly target leptin, is enriched in pathways related to leptin and insulin signaling, type 2 diabetes, and taste perception, among others in our data." (PMID 41047117, 2025). "An exploratory study also identified significant correlations between circulating oxytocin levels, specific gut microbiota species, and leptin in men with type 2 diabetes, suggesting a potential role for oxytocin in gut-brain axis signaling." (PMID 41561046, 2025). "NS oil supplementation in patients with type-2 diabetes mellitus also resulted in a significant drop in blood leptin concentration." (PMID 38178093, 2024). "Overall, data suggest that leptin signaling in the brain can help normalize diabetic hyperglycemia in people with type 2 diabetes." (PMID 38707092, 2024). "In adipokines, plant and marine sources of n‐3 PUFAs have been proved to increase adiponectin and decrease leptin levels in patients with type 2 diabetes." (PMID 37927197, 2024). "Plasma concentrations of hsCRP, IL-6, and leptin were higher in South Asians than in Nordics with normoglycaemia, but similar between the ethnicities in the prediabetes/type 2 diabetes group." (PMID 38786765, 2024). "Correlating these data, we can assume that CCL2, CCL5, IL-6, IL-1β, and leptin can play a significant role in MDSC recruitment in the adipose tissue of patients with type 2 diabetes." (PMID 39518420, 2024). "Canagliflozin has been shown to decrease serum leptin and IL-6 levels compared to glimepiride in patients with type 2 diabetes." (PMID 38566143, 2024). "This knowledge gap is highlighted by comparing insights into leptin biology with knowledge about the physiology and biochemistry of insulin action in type 2 diabetes." (PMID 38165042, 2024). "Leptin levels were already higher among patients with type 2 diabetes even with normal BMI, and were significantly higher in obese non-diabetic patients and were the highest in obese patients with type 2 diabetes." (PMID 36901837, 2023). "Adipose tissues secrete a lot of adipokines, such as leptin, resistin, and adiponectin which is closely related to type 2 diabetes because of its effect on insulin sensitivity and inflammation." (PMID 37371606, 2023). "As the ZDSD rat has an intact leptin pathway, the metabolic origin of the type 2 diabetes (T2D)-like state that spontaneously develops in the ZDSD rat strain is a more translatable model to the clinical metabolic syndrome in humans." (PMID 38069302, 2023). "Pathologically, leptin resistance and decreased sensitivity to leptin receptors depolarize islet β cells and promote insulin secretion, resulting in hyperinsulinemia and type 2 diabetes." (PMID 36998473, 2023). "boulardii to leptin-resistant obese and type 2 diabetic mice led to a reduction of body weight, fat mass, hepatic steatosis, and inflammatory tone." (PMID 37125045, 2023).
type 2 diabetes (continued). "Adipocyte-derived hormones, including adiponectin and leptin, increase insulin sensitivity, a vital step in the aetiology of type 2 diabetes." (PMID 36826001, 2023). "Leptin interferes with insulin signaling, and in type II diabetes, plasma leptin levels correlate with the degree of IR, a relationship independent of BMI and body fat mass." (PMID 36922570, 2023). "This study aimed to compare the attenuating effect of 8-week high intensity-interval training (HIIT) on type 2 diabetes (T2D)-induced CI between male and female rats with a special focus on adiponectin and leptin." (PMID 37758935, 2023). "In this manner, leptin resistance should lead to peripheral (adipose tissue, liver, and muscle) insulin resistance and islet beta-cell apoptosis, paving the way to Type 2 diabetes." (PMID 38260129, 2023). "So, for example, in patients with type 2 diabetes, for every percentage reduction in body weight, there was a 4.4% decrease in leptin, a 3.9% increase in adiponectin, and a 5.9% reduction in LAR." (PMID 35662920, 2022). "The leptin/adiponectin ratio, which positively correlates with type 2 diabetes, exhibited a decreasing trend in HFD-fed Ad-CIDECtg mice." (PMID 35963433, 2022). "In previous studies, CoQ10 supplementation significantly reduced leptin levels in individuals with non-alcoholic fatty liver disease and type 2 diabetes, which were inconsistent with our study." (PMID 35241098, 2022). "Genetic polymorphisms in the genes coding for leptin (LEP) and the leptin receptor (LEPR), particularly SNPs, have been demonstrated to be associated with adult obesity, childhood obesity or type-2 diabetes." (PMID 36289764, 2022). "Curcuminoids have been demonstrated in diabetes mellitus type 2 patients to improve insulin resistance, reduce glucose and insulin levels, enhance adiponectin secretion, and lower levels of leptin, resistin, interleukin (IL-6, IL-1β), and TNF-α." (PMID 35401176, 2022). "In one middle-east study, fasting-lipid-profile, hemoglobin A1c, serum leptin, insulin, and glucose levels were measured among type 2 diabetic patients." (PMID 36295022, 2022). "To date, a variety of adipokines related to type 2 diabetes have been discovered and identified, including Adiponectin, Leptin, Visfatin, IL-6 and FGF21, etc." (PMID 35712241, 2022). "Current study indicates the antioxidant and antidiabetic potential of E. helioscopia methanolic extract in normalizing the lipid profile, thyroid hormones, amylin, leptin, and carbohydrate metabolism in type 2 diabetic rat model." (PMID 35078449, 2022). "Renet al., on the other hand, discovered that in type 2 diabetes patients with the AA genotype, plasma levels of leptin and insulin were much lower than those with the GA or GG genotypes." (PMID 36128550, 2022). "This association between leptin and RAGE was previously demonstrated in a type 2 diabetes mouse model." (PMID 34214138, 2021). "The SNPscanTM kit is used to investigate SNP rs9891119 of the STAT3 gene in the leptin signaling pathway between type 2 diabetes patients and normal persons in Chinese Han population from Guangdong." (PMID 33833859, 2021). "In another study, Farr and coworkers found that 17 days of GLP-1 therapy reduced serum leptin levels in patients with type 2 diabetes mellitus (T2DM)." (PMID 34660808, 2021). "The results of studies showed that leptin concentration correlates positively with BW and Body mass index (BMI) in type 2 diabetes condition; our results were consistent with the findings of these studies." (PMID 34039404, 2021). "The increased secretion of leptin by the adipose tissue in type 2 diabetes was shown to enhance the aggregation and immunosuppressive ability of MDSC." (PMID 34975496, 2021). "Other mice models, such as ob/ob mice (leptin mutant) and db/db mice (leptin receptor mutant) are also commonly used as preclinical models of type 2 diabetes." (PMID 34082690, 2021).
type 2 diabetes (continued). "The function of linoleic acid relates with the regulation of body weight, and serum leptin in subjects with type 2 diabetes." (PMID 34959884, 2021). "There are studies that include PD + EX which conclude that the Paleolithic diet is a powerful tool to improve body composition and metabolic balance, including insulin sensitivity, glycemic control, and leptin in individuals with type 2 diabetes." (PMID 33801152, 2021). "Other breast milk components, such as the hormone leptin, are involved in infant appetite regulation, and long-chain polyunsaturated fatty acids facilitate brain development and are protective against type-2 diabetes (T2D)." (PMID 32903831, 2020). "Our results should inform future clinical trials that aim to reduce the burden of type 2 diabetes through the modification of serum levels of leptin and adiponectin." (PMID 32131811, 2020). "We report, that interval walking statistically significantly reduced albuminuria and leptin/adiponectin ratio, and had a moderate positive effect on HbA1c in patients with type 2 diabetes." (PMID 32652863, 2020). "Further investigation into leptin as a potential marker of future cardiovascular disease and type 2 diabetes in SCBT is needed." (PMID 32170116, 2020). "There is growing evidence from animal models that leptin and adiponectin play a critical role in type 2 diabetes prevention and control by promoting beta-cell function and survival, improving insulin sensitivity, and regulating glucose metabolism." (PMID 32131811, 2020). "Nevertheless, in a study from India, lower serum leptin levels in those with type 2 diabetes were partially due to increased waist circumference, decreased BMI, and male sex." (PMID 32131811, 2020). "In a study of 367 Mexican–Americans, type 2 diabetes was strongly related to elevated levels of IL-6, leptin, CRP and TNF-α, whereas higher glucose levels correlated positively and linearly with high levels of IL-6 and leptin." (PMID 32751810, 2020). "Twenty-four weeks of treatment with EPA 320 mg and DHA 200 mg daily showed beneficial effects on waist circumference, glucose metabolism, glycosylated hemoglobin, leptin, leptin/adiponectin ratio, and lipid profile among individuals with type 2 diabetes." (PMID 32796608, 2020). "Meta-analysis on 494 patients with type 2 diabetes from 10 articles concluded that plant and marine sources of n-3 PUFAs seem to boost adiponectin levels and decrease leptin." (PMID 32059381, 2020). "Plasma leptin levels are associated with the emotional state of individuals throughout the day and serum leptin and leptin resistance correlated with anxiety symptoms in patients with type 2 diabetes (T2D)." (PMID 32226410, 2020). "In Model 1, the hazard ratio of type 2 diabetes increased as quartiles of leptin increased, when compared to the reference first quartile (data not shown)." (PMID 32131811, 2020). "Endoplasmic reticulum (ER) stress has emerged as a critical mechanism involved in leptin resistance and type 2 diabetes in adult individuals." (PMID 32163401, 2020). "The Db/Db model is well accepted in the literature as a type 2 diabetes model, although other diabetic models exist and assessments of spinal pathologies in additional diabetic mouse models and/or leptin impairments would enable broadened interpretations." (PMID 32374776, 2020). "A limited number of observational population studies assessed the relationship of leptin with incident type 2 diabetes." (PMID 32131811, 2020). "In individuals with type 2 diabetes, adiponectin levels are decreased and leptin levels are increased due to leptin resistance." (PMID 32652863, 2020). "Recently, leptin-adiponectin ratio (l/a) emerged as a good predictor of MS and type 2 diabetes, stronger than leptin and adiponectin alone." (PMID 31151171, 2019).
type 2 diabetes (continued). "For example, 4-PBA was found to maintain blood homeostasis in type 2 diabetic mice by reducing the effects of ER stress and to improve the leptin response in the hypothalamus of obese mice by inhibiting UPR responses." (PMID 31853224, 2019). "It has been shown previously that a plant-based diet significantly lowers body fat and circulating leptin levels in healthy volunteers and in people with type 2 diabetes." (PMID 30871233, 2019). "Preclinical studies on rodent models of type 2 diabetes have shown how leptin treatment can regulate glucose homeostasis and reduce body weight and food intake." (PMID 30094465, 2018). "Multivariate analysis further revealed that, obese persons with type 2 diabetes were three times less likely to have elevated leptin levels than obese controls." (PMID 29422086, 2018). "Effects of ASE (200mg/Kg/day) and exercise training (30 min/day; 5 days per week) on glucagon-like peptide-1 (GLP-1), leptin, and anti-inflammatory cytokine serum levels in type 2 diabetic animals." (PMID 29920546, 2018). "We demonstrated that type 2 diabetes and gender were independent factors in determining serum leptin levels among obese subjects." (PMID 29422086, 2018). "Whilst women tended to show elevations in biomarkers related to an increased risk of type 2 diabetes (HOMA IR, leptin and TNF-α), men showed a marked increase in the cardiovascular disease risk biomarker CRP." (PMID 29190710, 2017). "Interactions between leptin and insulin signaling, and potential therapeutic uses for leptin in normalizing type 2 diabetes have been described recently." (PMID 28533765, 2017). "MUFA-rich high-fat diets (Mediterranean diet, 38% of energy) decreased serum leptin levels, but fasting and postprandial serum adiponectin and resistin remained unchanged in obese type 2 diabetic patients." (PMID 29048361, 2017). "Gender appeared to be an important factor modifying the leptin concentration in the blood plasma in all patients with type 2 diabetes." (PMID 28758947, 2017). "SGLT1 levels have been shown to be decreased by leptin in vitro in rat jejunal mucosa, as well as in vivo in the small intestine of an obese type 2 diabetic mouse model with hyperleptinaemia." (PMID 28421113, 2017). "Lithium, another anti-impulsivity drug, was found beneficial in correcting the glycemic parameters in diabetes mellitus type 2 (T2DM) by inhibiting glycogen synthase kinase-3 (GSK-3) a leptin-lowering enzyme." (PMID 28243210, 2017). "The concentrations of leptin in both P and PF were each related to type 2 diabetes, BMI, circulating levels of glycated hemoglobin and to treatment with an inhibitor of the renin-angiotensin system." (PMID 27139713, 2016). "Findings that leptin-deficient ob/ob mice and leptin receptor-defective db/db mice develop hyperinsulinelima before the onset of a type 2 diabetes phenotype led to discoveries that leptin also inhibits preproinsulin gene expression by β-cells." (PMID 27242781, 2016). "In fact, in a murine model of type II diabetes mellitus, downregulation of mitochondrial HSPD1 caused hypothalamic insulin resistance and mitochondrial dysfunction consequent to disruption of leptin signaling." (PMID 27125468, 2016). "Leptin is also a strong predictor of obese type 2 diabetes with BMI, WHR and oxidative stress status." (PMID 25897417, 2015). "Our data support the use of serum leptin in type 2 diabetes to add independent prognostic information in terms of ischemic heart disease when compared with traditional cardiovascular risk factors." (PMID 25994184, 2015). "The results of our study support further assessment in larger cohorts of the role of measuring leptin levels as a predictive marker if ischemic heart disease in the care of patients with type 2 diabetes." (PMID 25994184, 2015).
type 2 diabetes (continued). "To evaluate the effect of HET on inflammation and cardiovascular function in obese and type 2 diabetes rats, we next measured the levels of inflammatory cytokines, adiponectin, leptin and systolic blood pressure." (PMID 26003803, 2015). "Here, we investigated the mutual relationships among plasma leptin, visceral fat accumulation, and cardiac autonomic dysfunction in patients with type 2 diabetes." (PMID 26338087, 2015). "Leptin plasma levels were significantly reduced in daughters of patients with type 2 diabetes, who, in a 7-week training program, exercised a total of 1,450 min at 74% of their maximum heart rate." (PMID 25885799, 2015). "In conditions of central obesity that favors insulin resistance and type 2 diabetes, leptin sensitivity is diminished." (PMID 25225489, 2014). "Insulin sensitivity is improved following leptin administration, and leptin has been found to decrease glucagon levels in rat and mouse models of both type 1 and type 2 diabetes, contributing to the improvement in glycemic status." (PMID 24987413, 2014). "In humans, leptin administration had a minimal impact on glycemic control (HbA1c decreased from 8.01% to 7.96%) in patients with type 2 diabetes who maintained a stable weight over the 4 month study period." (PMID 24987413, 2014). "The serum leptin level in type 2 diabetic patients (19.32 ± 11.43 ng/mL) was significantly lower than that in non-diabetic subjects (32.16 ± 11.02 ng/mL)." (PMID 23853613, 2013). "In this study, the effect of atorvastatin treatment on the interaction between leptin and adiponectin, and on clinical parameters was examined in patients with type II diabetes." (PMID 24255692, 2013). "An early study showed decreased IL-1RA levels in type 2 diabetes, and it has been demonstrated that Leptin decreases β-cell production of IL-1RA, down-regulating IL-1RA expression in pancreatic β-cells in type 2 diabetes." (PMID 24148878, 2013). "Experimental studies showed that the leptin levels in patients with type 2 diabetes are diverse and seem to be related to the duration of the disease." (PMID 24260344, 2013). "In subjects with poorly controlled type 2 diabetes who lost weight rapidly, with lower levels of BMI and leptin, levels of TNF-α were reported to be higher than in controls." (PMID 24260344, 2013). "In conclusion, atorvastatin appears to exert multiple effects on the interaction between leptin, adiponectin and the L/A ratio, and clinical parameters, in patients with type II diabetes." (PMID 24255692, 2013). "It has been found that the majority of type 2 diabetes patients have higher levels of body fat, but normal or increased leptin in the plasma, indicating leptin resistance (LR)." (PMID 24455748, 2013). "Lipodystrophy leads to early type 2 diabetes and leptin reverses the metabolic consequences of the disease." (PMID 23781317, 2013). "In humans, atorvastatin lowered circulating leptin in patients with type II diabetes and increased adiponectin levels in individuals with a high cardiovascular risk." (PMID 24255692, 2013). "Conversely, enhancement of ER capacity augments leptin-stimulated LepRB activation, and increases insulin sensitivity and type 2 diabetes in obese mice." (PMID 22815920, 2012). "Another study noted micro- and macroalbuminuria patients with type 2 diabetes had higher leptin levels than normoalbuminuric patients." (PMID 22969168, 2012). "Here we show that there is strong evidence of inflammation with activation of inflammatory cytokines such as IL-6 and leptin in newly diagnosed type 2 diabetes." (PMID 22110481, 2012). "Cytokines including IL-1β, leptin, resistin, and adiponectin have been shown to play important roles in the development of pancreatic β-cell dysfunction and type 2 diabetes." (PMID 21113299, 2010). "Recently, Chen and colleagues have reported that overt type 2 diabetes in Akt1(+/−)Akt2(−/−) mice is due to markedly decreased leptin level and β-cell dysfunction." (PMID 21113299, 2010).